FBXW7 (F-box and WD repeat domain containing 7)
Diseases named in the same sentence as FBXW7 in open-access papers (continued):
Sharing a sentence is not in itself a finding about the gene and the disease.
chronic lymphocytic leukemia (7 papers, 2015 to 2024). "FBXW7 mutations reduce the binding of NOTCH1, leading to cleaved NOTCH1 accumulation and target gene activation in chronic lymphocytic leukemia." (PMID 38485719, 2024). "Similarly, USP28 prevents FBXW7 self-degradation in chronic lymphocytic leukemia (CLL), leading to elevated levels of Notch1." (PMID 39749199, 2024). "Similarly, we also observe co-mutations characteristic of chronic lymphocytic leukemia (CLL); 6 out of 16 (37.5%) cases of trisomy 12 co-occurred with a mutation in NOTCH1, MYD88, or FBXW7; 2 out of 9 (22%) deletions on chr13q co-occurred with a ATM mutation." (PMID 33436578, 2021). "Additionally, FBXW7 is a candidate cancer driver gene in chronic lymphocytic leukemia(CLL)." (PMID 38027013, 2023).
colitis (7 papers, 2018 to 2024). Inflammation of the colon. "The FBXW7/EZH2/CCL2/CCL7 pathway has been shown to exacerbate colitis severity by recruiting CX3CR1 proinflammatory MPhs." (PMID 39568749, 2024). "It has been reported that FBXW7 plays a key role in regulating colitis by inducing CCL2 and CCL7 expression in macrophages and promoting the accumulation of pro-inflammatory mononuclear macrophages." (PMID 35419455, 2022). "Consequently, during dextran sodium sulfate (DSS) or 2,6,4-trinitrobenzene sulfonic acid (TNBS)-induced colitis, the depletion of Fbxw7 in myeloid cells has been shown to mitigate colitis." (PMID 38434245, 2023).
Insulin resistance (7 papers, 2019 to 2025). Increased resistance towards insulin, that is, diminished effectiveness of insulin in reducing blood glucose levels. "Liver-specific Fbxw7 knockout mice presented hyperglycemia, glucose intolerance, and insulin resistance." (PMID 32095365, 2020). "Our results showed that Fbxw7 knockdown notably worsened hepatic inflammation and insulin resistance in HFD-fed mice." (PMID 31215394, 2019). "In conclusion, this study demonstrates a protective role of FBXW7 in the development and progression of NAFLD by attenuating inflammation and consequent insulin resistance, which is associated with the suppression of HMGB1-mediated innate immune signaling." (PMID 31215394, 2019). "MiR-223 has been found to be increased in populations with obesity and insulin resistance; furthermore, this miRNA was found to modulate the inflammatory phenotype and macrophage activation through the FBXW7/TLR4 (F-box and WD repeat domain containing 7/toll-like receptor 4) axis." (PMID 38132872, 2023). "Furthermore, we recently discovered an inverse relationship between the F-box/WD repeat-containing protein 7 (FBXW7) and affective symptoms, which was mediated by increased atherogenicity and insulin resistance." (PMID 35330475, 2022). "However, FBXW7 overexpression effectively improved the glucose intolerance and systemic insulin resistance in HFD-fed mice." (PMID 31215394, 2019). "MiR-223 has been well documented to connect insulin resistance and inflammation, and controls multifactorial signals connected with F-box and WD repeat domain containing 7 (FBXW7), toll-like receptor 4 (TLR4), and STAT to alleviate insulin resistance and obesity pathogenesis." (PMID 31847392, 2019). "Our results demonstrate a protective role of FBXW7 in NAFLD by abating HMGB1-mediated innate immune signaling to suppress inflammation and consequent insulin resistance, suggesting that FBXW7 is a potential target for therapeutic intervention in NAFLD development." (PMID 31215394, 2019). "In this study, we found that fat FBXW7 overexpression in mice showed reduced S6K1 and p-S6K1 levels in BAT and iWAT, accompanied with impaired insulin resistance." (PMID 39747664, 2025). "Our results revealed that FBXW7 overexpression attenuated hepatic inflammatory response and insulin resistance in HFD-fed mice, while FBXW7 knockdown exacerbated these disorders." (PMID 31215394, 2019). "In this study, we hypothesized that FBXW7 ameliorates the development and progression of NAFLD through abating HMGB1-mediated innate immune signaling to suppress inflammation and consequent insulin resistance." (PMID 31215394, 2019).
medulloblastoma (7 papers, 2018 to 2025). A malignant, invasive embryonal neoplasm arising from the cerebellum. "We then evaluated the expression of MYC, PLK1, and FBXW7 in a panel of well-characterized medulloblastoma cell lines." (PMID 33494392, 2021). "Additional targets of FBXW7, including AURORA A MCL-1, and Cyclin E, were also downregulated in response to PCM-075 in MB cells, implying FBXW7 is an upstream regulator of c-MYC in medulloblastoma." (PMID 33494392, 2021). "FBXW7 acts as a tumor suppressor in MYC-amplified medulloblastoma: the overexpression of FBXW7 induces cell apoptosis, suppresses cell proliferation, and improves the survival of orthotopic xenograft bearing mice." (PMID 33494392, 2021). "Altogether, these findings demonstrated that PLK1 inhibition stabilizes FBXW7 in MYC-driven MB, thus revealing an important function of FBXW7 in suppressing medulloblastoma progression." (PMID 33494392, 2021). "To establish the role of FBXW7 in medulloblastoma, we performed microarray analysis in 44 MB patient samples and six normal cerebella samples." (PMID 33494392, 2021). "Overexpression of FBXW7 enhances the apoptosis of the medulloblastoma cells." (PMID 36998461, 2023). "In order to evaluate whether Thr205 residue phosphorylation affects the function of FBXW7 in medulloblastoma, we constructed WT-FBXW7 and phosphomimetic aspartic acid mutant (T205D) and performed a cell proliferation assay in D458 cells." (PMID 33494392, 2021). "Our results demonstrated that PLK1 inhibition enhanced FBXW7 stability in medulloblastoma." (PMID 33494392, 2021). "Our study identified FBXW7 as a critical suppressor in the tumorigenesis of medulloblastoma." (PMID 33494392, 2021). "In MYC−driven medulloblastoma, inhibition of PLK1 stabilizes FBXW7, underscoring its tumor‐suppressive function, while blocking ELK1−mediated transcription activates FBXW7 and suppresses MCL1, leading to cytotoxicity." (PMID 40370434, 2025). "A similar PLK1/Fbxw7/Myc axis was also identified in c-MYC-driven medulloblastoma, with PLK1 antagonizing Fbxw7-mediated c-Myc degradation." (PMID 36902175, 2023). "Thus, FBXW7 may modulate apoptosis by promoting MCL-1 degradation in medulloblastoma." (PMID 33494392, 2021). "Group 3 cell lines expressed lower levels of the FBXW7 protein and higher levels of the PLK1 and MYC proteins compared with the SHH group or normal cerebellum, further confirming the inverse relationship of FBXW7 and MYC/PLK1 in medulloblastoma." (PMID 33494392, 2021). "Together, these data indicated that FBXW7 physically interacts with PLK1 and c-MYC, and it induces the ubiquitination and proteasome degradation of PLK1 and c-MYC in medulloblastoma." (PMID 33494392, 2021). "Furthermore, SOX9 protein was also targeted by FBXW7 for proteasomal degradation in medulloblastoma cells even under normal unstressed conditions, suggesting that FBXW7-mediated SOX9 degradation might be in a cell and context dependent event, and not specific to DDR." (PMID 34760892, 2021).
neuroblastoma (7 papers, 2012 to 2024). Neuroblastoma (NB) is the most common solid, extracranial childhood tumor. "Stimulation with FNIII14 not only upregulates the expression of Fbxw7, but also downregulates the expression of Aurora A in neuroblastoma cells." (PMID 31452837, 2019). "The FBXW7 E3-ubiquitin ligase is an important regulator of MycN stability in neuroblastoma cells." (PMID 30542116, 2019). "AURKA prevented the Fbxw7-mediated degradation of MYCN, which facilitated the growth of MYCN-amplified neuroblastoma cells." (PMID 38287009, 2024). "A PLK1/FBXW7/N-MYC pathway has been demonstrated in neuroblastoma, where PLK1 phosphorylates FBXW7, promotes FBXW7 degradation and leads to the stabilization of N-MYC." (PMID 33494392, 2021).
Obesity (7 papers, 2021 to 2025). Accumulation of substantial excess body fat. "Taken together, these data suggested that FBXW7 deficiency in adipose tissues protected mice from HFD induced obesity, possibly due to the combined effects of enhanced BAT expansion and browning of white fat for enhanced thermogenesis and energy expenditure." (PMID 39747664, 2025). "By studying FBXW7 fat conditional transgenic and deficient mice, we demonstrated that FBXW7 promoted obesity and metabolic dysfunctions by targeting S6K1, a downstream effector of mTOR signaling, in thermogenic fat, which consequently impact preadipocyte proliferation via glycolytic product lactate." (PMID 39747664, 2025). "Our results suggested that adipose FBXW7 is a major regulator for thermogenic fat biology and energy homeostasis, which provides potential therapeutic target for obesity and metabolic diseases." (PMID 39747664, 2025). "FBXW7 overexpression in fat suppresses energy expenditure and thermogenesis, thus aggravates obesity and metabolic dysfunctions in mice." (PMID 39747664, 2025). "In summary, we provide evidence that adipose FBXW7 acts as a major regulator for thermogenic fat biology and energy homeostasis and serves as potential therapeutic target for obesity and metabolic diseases." (PMID 39747664, 2025). "Conversely, FBXW7 depletion in fat leads to brown fat expansion and browning of white fat, and protects mice from diet induced obesity, hepatic steatosis, and hyperlipidemia." (PMID 39747664, 2025). "Of clinical significance, we also found that both mRNA and protein levels of FBXW7 were increased in subcutaneous WAT of obese human, and was negatively correlated with Ucp1 levels, suggesting FBXW7 is involved in the suppression of thermogenic functions and the development of obesity." (PMID 39747664, 2025). "The miRNA miR-223 has been implicated in IR and obesity by modulating STAT signaling pathways, the toll-like receptor 4 (TLR4), and the F-box/WD repeat-containing protein 7 (FBXW7), a negative regulator of adipogenesis and a tumor suppressor in many cancer types." (PMID 34681797, 2021). "We also analyzed the expression of FBXW7, MBOAT2, STXBP4, SPARCL1, and UTS after SLFN12 overexpression because these are obesity-related genes." (PMID 36291149, 2022).
virus infection (7 papers, 2017 to 2025). "Deletion of FBXW7 in macrophages resulted in dowregulated K48-linked ubiquitination of SHP2 during viral infection." (PMID 28287082, 2017). "Recently, FBXW7 has also been shown to have multiple functions in virus infection via interacting with diverse host molecules such as SHP2, mTOR, and NS5B in immune responses." (PMID 35651754, 2022). "We report here that, upon virus infection, the E3 ubiquitin ligase FBXW7 translocates from the nucleus into the cytoplasm and stabilizes RIG-I." (PMID 28287082, 2017). "To further confirm the role of interaction of SHP2 with FBXW7 in virus infection, we compared IFN-β expression in macrophages from Lysm+SHP2f/f and SHP2f/f mice that infected with VSV." (PMID 28287082, 2017). "Here the authors show that, upon virus infection, FBXW7 interacts with RIG-I and inhibits ubiquitin-mediated degradation of RIG-I, resulting in increased interferon signalling in vitro and in vivo." (PMID 28287082, 2017). "Cell cycle regulation plays an important role in cell growth and viral infection progression; thus, circ-FBXW7 may exert antiviral effects by targeting mir-338y to regulate cell cycle-related genes." (PMID 37841466, 2023). "It indicates that FBXW7 regulates RIG-I signalling through SHP2/RIG-I instead of SHP2/TBK1, as the interaction between SHP2 and RIG-I was enhanced and predominant during virus infection." (PMID 28287082, 2017). "Moreover, several novel genes score in the top 20 for multiple strains, including UBE2M, MBNL1, FBXW7, PCGF1, and PPP2CA, implicating those gene products in processes important for viral infection across HIV-1 strains." (PMID 36744886, 2023). "Thus, the nucleocytoplasmic translocation of nuclear proteins, such as FBXW7 and MLL5, illustrates an important mechanism for precise regulation of innate immune responses during virus infection." (PMID 29593341, 2018).
Colorectal tumor (6 papers, 2013 to 2024). "Colorectal tumor mutation profiling showed a missense mutation of FBXW7 in chromosome number 4 with a change in the amino acid sequence R425C." (PMID 30791487, 2019). "The ATR, CHEK1 and CDC7 synthetic lethal effects can be replicated using small molecule inhibitors and in addition, the CDC7 dependency of colorectal tumour cell lines with reduced FBXW7 mRNA expression in the DepMap dataset was seen." (PMID 37866880, 2024). "The FBXW7 mRNA level was found to be considerably lesser in colorectal tumor tissues compared to the corresponding normal tissues." (PMID 30791487, 2019). "High CRY2 and low FBXW7 expression in colorectal tumour tissue was correlated with chemoresistance as well as poorer survival of CRC patients." (PMID 26768731, 2016).
liver cancer (6 papers, 2022 to 2025). An epithelial or non-epithelial malignant neoplasm that arises from the liver. "FBXW7 plays a tumor supporter role in multiple tumors, and increased FBXW7 has been confirmed to be closely related with resistance of liver cancer cells on sorafenib." (PMID 36193503, 2022). "In addition, FBXW7 was found to be a downstream target of miR-367 in liver cancer cells." (PMID 40534867, 2025). "Therefore, CASC2 regulates the expression of FBXW7 by regulating miR-367 in liver cancer cells." (PMID 40534867, 2025).
brain cancer (5 papers, 2019 to 2023). A primary or metastatic malignant neoplasm affecting the brain. "For example, FBXW7‐185aa, encoded by circ‐FBXW7, has potential prognostic implications in brain cancer, and the protein encoded by circ‐ZNF609 can specifically control myoblast proliferation." (PMID 35770323, 2022).
carcinosarcoma (5 papers, 2014 to 2025). A malignant tumor composed of a mixture of carcinomatous and sarcomatous elements. "In vivo evidence has demonstrated that the co-inactivation of Fbxw7 and Pten in murine models leads to stepwise progression from endometrioid intraepithelial neoplasia to invasive adenocarcinoma and, ultimately, to carcinosarcoma." (PMID 40725576, 2025). "While deletion of Fbxw7 alone did not induce neoplasia by 52 weeks age, co‐deletion with Pten caused aggressive tumours resembling carcinosarcomas in all cases by 40–67 weeks age." (PMID 37589076, 2023). "Notably, all resulting carcinosarcomas exhibited heterologous sarcomatous elements, suggesting that FBXW7 may also contribute to the development of heterologous components." (PMID 40725576, 2025).
colon adenocarcinoma (5 papers, 2014 to 2026). "In the ERK1/2 signaling pathway, E3 ligases RNF149 and FBXW7 regulate the stability of B-Raf in colon adenocarcinoma (COAD), leading to its degradation." (PMID 39048965, 2024). "Data from timer 2.0 show that the expression of FBXW7 displays a positive correlation with macrophages infiltration level in colon adenocarcinoma (COAD)." (PMID 35814468, 2022).
gastric tumors (5 papers, 2013 to 2023). "The incidence of gastric tumors in Fbxw7+/− mice was much higher than in wild-type mice (13/20 vs 6/20, P = 0.056)." (PMID 28422719, 2017). "In the present study, we observed only one copy of the FBXW7 gene in 45.16% of the gastric tumors studied." (PMID 24053468, 2013). "One copy deletion of Fbxw7 gene with a frequency of 45.5% was observed in gastric tumors." (PMID 28422719, 2017). "Considering the role of c-Myc in promoting cell transformation, this may be one of the reasons why Fbxw7+/−mice developed more gastric tumors than controls." (PMID 28422719, 2017). "Since c-MYC protein is degraded via FBXW7-mediated ubiquitin pathway, we examined the protein expression of FBXW7 and c-MYC in gastric tumors and paired normal tissues from six patients and mouse models." (PMID 28422719, 2017).
metastatic disease (5 papers, 2013 to 2025). "The primary and metastatic tumours demonstrated the somatic mutations FBXW7 Q242H, FBXW7 S582L as well as KDM6A S763I and PIK3C2B Q877_W878K, suggesting the possibility of bi-allelic FBXW7 loss resulting in a high level of MYC protein expression, which was documented in the metastatic tumour." (PMID 33311588, 2021). "Whereas, FBXW7 overexpression not only led to markedly decreased number of mice with distant metastasis, but also dramatically decreased the number of metastatic tumors in both lung and liver of each mouse." (PMID 25749036, 2015). "Mutations appear enriched in early-stage, organ-confined CRC compared with metastatic disease; patients without distant metastases show a higher incidence of FBXW7 and NOTCH pathway alterations." (PMID 41373479, 2025).
oral squamous cell carcinoma (5 papers, 2020 to 2024). "In oral squamous cell carcinoma, FBXW7 has been reported to negatively regulate MCL-1 expression and autophagy." (PMID 39749199, 2024). "The expression of FBXW7 is decreased in oral squamous cell carcinoma (OSCC) tissues and shows diagnosis value." (PMID 37249289, 2023). "For example, FBXW7 inhibits the epithelial-mesenchymal transformation of oral squamous cell carcinoma cells through PI3K/AKT signaling pathway." (PMID 35965327, 2022). "Further, it has shown that overexpression of FBXW7 can reduce cell proliferation, migration and lumen formation in oral squamous cell carcinoma." (PMID 33369138, 2021). "Furthermore, reduced FBXW7 expression decreases cisplatin sensitivity in oral squamous cell carcinoma." (PMID 39749199, 2024).
sarcoma (5 papers, 2019 to 2025). A usually aggressive malignant neoplasm of the soft tissue or bone. "In contrast, the uterine epithelial-specific ablation of Fbxw7 and Pten in mice resulted in the development of “heterologous” CS, having a sarcoma component of differentiation toward bone and cartilage in half of the cohorts in three months." (PMID 34172714, 2021). "Consistent with human sarcoma spheroid models, KCa1.1 protein degradation was suppressed by the downregulation of FBXW7 in LNCaP spheroids." (PMID 34948357, 2021). "In sarcoma spheroid models, the downregulation of F-box/WD repeat-containing protein 7 (FBXW7) decreased the protein degradation of KCa1.1, which increased KCa1.1 activity." (PMID 34948357, 2021). "Analyses revealed that the tumors not only harbored mutations characteristic of sarcoma, such as RB1 (50%), ATRX (38%), and FBXW7 (17%) mutations, but also possessed mutations commonly associated with endometrial adenocarcinoma, including PTEN (42%), PIK3CA (42%), and AKT (17%) mutations." (PMID 41181577, 2025).